INS (insulin)
Diseases named in the same sentence as INS in open-access papers (continued):
Sharing a sentence is not in itself a finding about the gene and the disease.
diabetes (continued). "Individuals with diabetes experience elevated levels of blood glucose due to a lack of insulin." (PMID 37954853, 2023). "Additionally, analysis in the current study demonstrated a higher usage of insulin in individuals with MA as compared to those without, indicating the challenge of managing their diabetes through OHD alone." (PMID 37692611, 2023). "Diabetes is one of metabolic diseases in which a person has high blood sugar, either because the body does not produce enough insulin, or because cells do not respond to the insulin." (PMID 36829795, 2023). "Moreover, certain antidiabetes medications, such as insulin, have been shown to increase weight gain in patients whose diabetes did not improve even after LSG." (PMID 36626105, 2023). "To date, no data are available on the prognostic role of the various diabetes statuses (diabetes on insulin vs diabetes not on insulin vs no diabetes) on clinical outcome in the setting of real-world clinical practice related to AF patients receiving non-vitamin K antagonist anticoagulants (NOACs)." (PMID 35976428, 2023). "Similarly, real-world data reported a significant reduction in HbA1c, which was achieved after switching to insulin degludec, irrespective of the type of diabetes and the type of prior long-acting insulin, and with lower insulin requirements." (PMID 36601214, 2023). "This study demonstrates that the use of dissolving patches for insulin delivery achieves a satisfactory relative bioavailability (RBA) compared to conventional subcutaneous injection, demonstrating the effectiveness of dissolving patches for diabetes treatment." (PMID 37109736, 2023). "Given previously reported species differences in HNF1A-deficiency phenotypes, the potential variability introduced by chemically induced diabetes, and the ability to distinguish between circulating human and mouse insulin via ELISA, we transplanted human pseudoislets in nondiabetic mice." (PMID 37943614, 2023). "Although the incidence and prevalence of diabetes were low in economically less developed countries, the lack of access to drugs (especially insulin, which is essential for type 1 diabetes) and surveillance technologies in these countries led to high rates of mortality and disability." (PMID 37400673, 2023). "Diabetes mellitus is a phenomenon in which ingested glucose is not absorbed in the body, accumulates in the blood, and is excreted in the urine due to insufficient secretion or poor secretion of insulin for various reasons." (PMID 37111730, 2023). "Interestingly, the down-regulation of BAG3 in beta cells was found to increase insulin secretion in response to glucose stimulation, and in this context, the decreased levels of BAG3 mRNA in diabetics may be required for facilitating insulin secretion." (PMID 37569434, 2023). "Recently, it has also been hypothesized that hyperinsulinemia present in the IR condition of obese subjects who have not yet developed diabetes may be due to altered insulin clearance, while insulin secretion remained unmodified." (PMID 37298967, 2023). "The prevalence of diabetes mellitus was 37.1%, all not insulin dependent." (PMID 36050624, 2023). "Therefore, GLP−1 agonists can be used as a drug in diabetes treatment by mimicking the hormone GLP−1 and binding to GLP−1 receptors on beta cells, which stimulates glucose-dependent insulin secretion from pancreatic islets, leading to a reduction in blood glucose levels." (PMID 36839746, 2023). "Latent autoimmune diabetes in adults (LADA) is a type of diabetes mellitus (DM) showing overlapping characteristics between type 1 DM (T1DM) and type 2 DM (T2DM), and autoimmunity against insulin-producing pancreatic cells." (PMID 36758065, 2023). "As such, hyperinsulinemia in obesity and diabetes results in the development of steatosis through increasing hepatic lipogenesis; subsequently, the accumulation of hepatic lipid species, e.g., diacylglycerol (DAG) and ceramide, leads to the impairment of insulin signaling." (PMID 36836874, 2023).
diabetes (continued). "For instance, in the setting of hypoglycemia, a common side effect of insulin and insulin secretagogues used in the treatment of patients with diabetes, the balance between positive and negative primers is acutely offset, resulting in an acutely decreased threshold for platelet activation." (PMID 36830610, 2023). "Furthermore, while the majority of participants (72.3%) reported using insulin pumps in their diabetes care, a majority of participants (69.9%) reported not using a continuous glucose monitor in their diabetes care in the past 30 days." (PMID 37111199, 2023). "Besides, diabetes is a chronic noncommunicable disease (NCD) that occurs when the pancreas produces insufficient insulin (the hormone that regulates the body's blood sugar level) or the body cannot effectively utilize the insulin produced." (PMID 37091043, 2023). "More recently, through the International Diabetes Federation projects, an Asian-specific mtDNA variation, m.1382A>C, was found to lead to a K14Q amino acid replacement in MOTS-c (mitochondrial open reading frame of the 12S rRNA-c), which is an insulin-sensitizing mitochondrial-derived peptide." (PMID 36671511, 2023). "Furthermore, lack of diabetes control and adequate insulin therapy often promotes diabetes-related family conflict, poor academic performance, and/or increased interpersonal conflict." (PMID 37468976, 2023). "The yearly incidence of ischemic stroke/TIA/systemic embolism was 0.86% in patients without diabetes, 0.87% in diabetic patients not receiving insulin (p = 0.92 vs no diabetes) and 1.81% in those on insulin (p = 0.002 vs no diabetes; p = 0.014 vs diabetes not on insulin)." (PMID 35976428, 2023). "However, unlike diabetes, this defect does not affect the production of insulin but the ability of insulin to activate PI3K." (PMID 38983593, 2023). "Differences in the pattern of other glucose lowering medication prescribing with insulin in people with type 1 and type 2 diabetes could not be accurately assessed because the Study did not collect information on diabetes type." (PMID 37874829, 2023). "Overall mortality was 3.36%/year in patients without diabetes, 5.02%/year in those with diabetes without insulin therapy (HR 1.50, 95% CI 1.27–1.75, p < 0.0001 vs no diabetes) and 8.91%/year in insulin-treated patients (HR 2.66, 95% CI 2.14–3.30, p < 0.0001 vs no diabetes)." (PMID 35976428, 2023). "Under normal settings, insulin triggers the lipoprotein lipase enzyme that separates triglycerides; however, in diabetes, lipoprotein lipase is not stimulated because of insulin inadequacy, hence producing hypertriglyceridemia which is a leading cause of cardiac disorders." (PMID 37110767, 2023). "However, insulin action in diabetes on the liver follows glycogen storage which was not tested in the histological study." (PMID 37692463, 2023). "One hundred and eighty rats were randomly allocated into 3 groups with 60 animals each: Control group (C): Animals without diabetes; Diabetes Group (D): Animals with uncontrolled induced diabetes; Controlled Diabetes Group (CD): Animals with diabetes induced controlled by the insulin administration." (PMID 38133472, 2023). "We obtained genetic associations of fasting insulin and fasting glucose from MAGIC only including individuals without diabetes, which may underestimate the associations." (PMID 36624450, 2023). "Fourth, despite the study targeting diabetic patients, we could not consideration of the severity of diabetes, disease duration, number of medications, usage of insulin, family history, or presence of complications." (PMID 36609387, 2023). "Age, gender, BMI, smoking, duration of diabetes, hypertension, low-density lipoprotein cholesterol (LDL-C), hypersensitive C-reactive protein (hs-CRP), anemia, diabetic neuropathy, DN, ASCVD, low education, OAD, insulin, and ACEI/ARB were included as covariates in the multivariable analysis." (PMID 38020197, 2023).
diabetes (continued). "Finally, insulin-requiring subjects demonstrated a higher 3D-SI than diabetic subjects not taking insulin or those without diabetes (DM on insulin: 0.63 ± 0.15 vs. DM not on insulin: 0.57 ± 0.14 vs. non-DM: 0.55 ± 0.13; P = 0.001)." (PMID 37542280, 2023). "This could be attributed to different reimbursement policies between countries influencing the population included in the analysis; for instance, only T1DM users or all patients using intensive insulin therapy regardless of the type of diabetes." (PMID 38003943, 2023). "These percentages highlighted the unmet needs in managing T2DM patients in Egypt, which could be attributed to the delay of insulin therapy, overuse of human insulin, overuse of vials, lack of diabetes education, and lack of healthcare support." (PMID 37264625, 2023). "Moreover, SARS-CoV-2 triggers autoimmunity, meaning that both autoantibody-positive insulin-dependent and autoantibody-negative diabetes can develop during an infection with the novel coronavirus." (PMID 37510181, 2023). "The study population we selected, comprising pregnant women without diabetes, may include some cases of mild gestational diabetes diagnosed midgestation and without insulin treatment." (PMID 38085559, 2023). "Diabetes mellitus (DM) is a chronic metabolic disease in which either the pancreas produces very little or no insulin, or the target cells of the body do not respond correctly to the insulin produced, resulting in high levels of glucose in the blood and urine." (PMID 36815184, 2023). "Physicians thought that newly diagnosed patients, sicker patients—those who had been hospitalized for diabetes, were currently using insulin, or who had any comorbid condition—and patients who were nonadherent to treatment were most likely to benefit from CES use." (PMID 38032701, 2023). "Moreover, peri‐donation glycated haemoglobin levels showed that donor insulin use in pancreas donors was not explained by pre‐existing undiagnosed diabetes." (PMID 37646197, 2023). "In individuals without diabetes, hypoglycemia is usually countered by a highly integrated defense system which includes reduced insulin secretion, increased release of glucagon, glucocorticoids, epinephrine, norepinephrine, and GH, and stimulation of the sympathetic nervous system." (PMID 37334290, 2023). "Additionally, between both groups of T2DM patients, individuals on insulin treatment had a longer diabetes duration than those without (P < 0.001)." (PMID 37542280, 2023). "Diabetes typically develops when the pancreas does not create enough insulin, or the organs involved in glucose metabolic regulation do not effectively respond to the insulin." (PMID 36904097, 2023). "When diabetes duration is over one year, the overall effect of self-monitoring of blood glucose on glycemic control in patients with type 2 diabetes who are not using insulin is small up to 6 months after initiation and subsides after 12 months." (PMID 38068801, 2023). "If insulin is absent or its action is impaired due to tissue insensitivity, cells, and tissues are unable to uptake glucose, which results in its accumulation in the blood, and consequently, diabetes symptoms occur." (PMID 36836817, 2023). "We did not evaluate patients with T2DM who were on insulin or who had other types of diabetes." (PMID 37241220, 2023). "Leaf extract reduced the levels of blood sugar in diabetes-induced albino rats, decreased levels of blood glucose, total cholesterol, glucose-6-phosphatase, glycated hemoglobin, fructose-1-6-bisphosphatase, and triglyceride, and increased levels of HDL cholesterol, insulin, and hexokinase." (PMID 37894680, 2023). "At multivariate analysis, diabetes on insulin was associated with a higher rate of ischemic stroke/TIA/systemic embolism [adjusted HR 2.20, 95% CI 1.37–3.54, p = 0.0011 vs no diabetes + diabetes not on insulin] and all-cause death [aHR 2.13 (95% CI 1.68–2.68, p < 0.0001 vs no diabetes]." (PMID 35976428, 2023).
diabetes (continued). "Compared to type 1 diabetes mellitus (T1D), where is a minute amount or no insulin remaining." (PMID 36672202, 2023). "Madecassoside improves insulin sensitivity in pancreatic cells to promote glucose‐stimulated insulin secretion (GSIS) and to enhance expression of insulin signalling proteins without any cytotoxic effects, making it a favourable drug compound in targeting type 2 diabetes mellitus." (PMID 36756687, 2023). "Moreover, certain species of Firmicutes have been shown to improve insulin sensitivity, reduce fat accumulation, and lower blood lipid levels by regulating the level of GLP-1 in the gut, thus preventing metabolic diseases such as diabetes and obesity." (PMID 37792060, 2023). "However, the insulin requirement level was controlled by the doctors and returned to normal at discharge, and there were no adverse events according to uncontrolled diabetes in the patients." (PMID 36673839, 2023). "Diabetes is a complex syndrome characterised by hyperglycaemia induced by an altered secretion of insulin or by a poor insulin action when the pancreas does not produce enough insulin or when the body cannot effectively use the insulin it produces, or both cases." (PMID 38136211, 2023). "However, most medications are specific to a particular disease, such as insulin and oral antidiabetic drugs, which should not be prescribed to individuals who do not have diabetes." (PMID 37915465, 2023). "It was observed that participants on insulin treatment modality, combined therapy (oral hypoglycaemic agent and insulin), participants without diabetic complication and participants without family history of diabetes had higher knowledge of diabetes." (PMID 36464636, 2023). "In diabetic patients withdrawn from insulin treatment for 24 h, renal amino acid exchange was similar to that of healthy individuals, suggesting also that the kidney was not an important gluconeogenic organ in human diabetes." (PMID 38201949, 2023). "Animals with STZ-induced diabetes do not require insulin to survive." (PMID 36829539, 2023). "Development of prediabetes was classified based on an increase in plasma glucose without a substantial change in insulin resistance, while diabetes was defined by severe hyperglycemia and impaired insulin signaling with rats exhibiting both hypoinsulinemia and insulin resistance." (PMID 37233701, 2023). "Type 1 diabetes mellitus (T1DM) is an endocrine disorder, whereby pancreatic β cells undergo autoimmune destruction and eventually stop producing insulin; this eventually leads to extreme insulin shortage, followed by several metabolic dysfunctions, specifically poor glucose homeostasis." (PMID 37965322, 2023). "In a single-arm multicenter pilot trial, we tested the feasibility, safety, and effectiveness of the Omnipod 5 AID System with real-time continuous glucose monitoring (CGM) for up to 10 days in hospitalized patients with insulin-requiring diabetes on nonintensive care unit medical–surgical units." (PMID 37578778, 2023). "Despite the hyperglycemia, mice with STZ-induced diabetes did not become insulin-resistant." (PMID 36722656, 2023). "Diabetes, defined by persistent hyperglycemia, is a metabolic syndrome that develops when the pancreas either secrete insufficient insulin or the body no longer effectively utilizes secreted insulin." (PMID 37663139, 2023). "Moreover, insulin therapy statistically varied across the TyG index quartiles (P = 0.025) without obvious differences in sex, age, diabetes duration or BMI among groups (P > 0.05)." (PMID 36890516, 2023). "While these physiological functions of dietary fiber justify its increasing consumption in diabetes prevention and management, reported observational data do not clearly identify its role in glycemic control and insulin sensitivity in context of a habitual diet in adults with and without T1D." (PMID 37960272, 2023).
diabetes (continued). "Moreover, although intensified insulin treatment regimens can ameliorate glycated hemoglobin levels, they do not provide protection against diabetes complications." (PMID 38111575, 2023). "According to our previous findings, magnesium sulfate (MgSO4) therapy can improve insulin sensitivity by increasing GLUT4 (glucose transporter number 4) gene expression and furthermore, MgSO4 administration in STZ-induced diabetic rat model could improve renal function." (PMID 36755074, 2023). "In female children without diabetes, reduced insulin sensitivity during puberty is compensated by increased endogenous secretion, whereas in type 1 diabetes the reduced sensitivity leads to a higher insulin need and might cause worse glycaemic control." (PMID 36700969, 2023). "Furthermore, diabetes remission (normal or near normal blood glucose levels in the absence of insulin therapy) was observed in 7 out of 10 patients started on the adjunct CT within 12 months after the start of insulin therapy." (PMID 37293502, 2023). "Excluded from the review were non-randomized trials, studies that did not report relevant outcomes for the clinical inquiries, research involving children or individuals below 18 years, investigations not using insulin as a diabetes treatment, and duplicate studies." (PMID 38077677, 2023). "The term encompasses a broad continuum, ranging from individuals who maintain normal glucose homeostasis due to increased endogenous insulin production and do not yet have diabetes, to individuals with diabetes who require exogenous insulin to maintain glucose homeostasis." (PMID 37301876, 2023). "Moreover, recent clinical guidelines from the American Diabetes Association and American Association of Clinical Endocrinology now endorse CGM use in individuals treated with nonintensive insulin regimens." (PMID 37471068, 2023). "Given this patient’s age of <25 years, presence of diabetes in two consecutive family generations, absence of β-cell autoantibodies, and preserved endogenous insulin secretion with a serum C-peptide level of >200 pmol/L, he met the criteria for consideration of a diagnosis of MODY." (PMID 37855645, 2023). "As this is study is a retrospective study based on hospital records, data on a diet, physical activity, income, number of births, household members, time of diabetes, and previous insulin use could not be presented." (PMID 37252703, 2023). "Although scientists do not know why, diabetes may interfere with the ability of the brain to respond to insulin." (PMID 37508471, 2023). "In fact, IR has been described in conditions not related to obesity or diabetes, such as starvation, malnutrition, chronic renal failure, where insulin levels may be normal or low." (PMID 37715242, 2023). "In addition, it is worth noting that our study did not include monitoring several key markers of diabetes and its complications, including glycated hemoglobin and insulin in the blood." (PMID 37569337, 2023). "An absolute lack of insulin will continuously raise the blood sugar level, resulting in diabetes." (PMID 37504259, 2023). "However, we confirmed the similar rates of MI in patients with diabetes without insulin therapy and in those without diabetes." (PMID 35976428, 2023). "Furthermore, there is evidence of a link between prolonged abnormalities in blood glucose levels (hyperglycemia), lack of insulin content, and insulin resistance in the brain in diabetes-mellitus that is related to cognitive dysfunction." (PMID 36831708, 2023). "Diabetes technology significantly increased yearly diabetes costs compared to no technology: insulin pumps € 4,759 (28.7% of children), Real-Time Continuous Glucose Monitoring € 7,259 (2.1% of children), and the combination of these treatment modalities € 9,579 (27.3% of children)." (PMID 37029362, 2023).